CD4 (CD4 molecule)
Diseases named in the same sentence as CD4 in open-access papers (continued):
Sharing a sentence is not in itself a finding about the gene and the disease.
infection (continued). "Both CD8+ and CD4+ memory T cells generated after natural infection or vaccination are important for parasite control." (PMID 39781380, 2024). "CD4+ TRM cells are potently induced through natural infection or wP vaccination, but relatively weakly by aP vaccination." (PMID 38276680, 2024). "A similar increase in IL-18 was observed 6 days post-treatment in the repeat blood stage infection study and its expression pattern correlated with activated CD4+ and activated regulatory T cells." (PMID 38890271, 2024). "This analysis also captured stages of infection (CD4lowp24low), where CD4 is already downmodulated, while env mRNA expression intensifies, suggesting that CD4 downmodulation precedes env mRNA expression." (PMID 39373535, 2024). "In right vagotomized mice, this included an increase in number of natural killer (NK) cells (day 3 post-infection), alveolar macrophages (AM) and B cells (day 8 post-infection), and the reduction of CD4 and NK T-cells at days 3 and 5, respectively." (PMID 38626267, 2024). "This reactivity increases as the infection evolves toward the hyperergic pole (CD4+/Th1-type) of that spectrum represented by ML." (PMID 39334233, 2024). "INFγ, TNFα, and IL-17-positive CD4+ T cells population only increased at an early stage of infection by WT and CNA25 suggesting their role in fungal clearance and early immune activation (Fig. 7Aiii,iv,v)." (PMID 38783167, 2024). "CD4+ T lymphocytes are one of these immune cells, playing a critical role in coordinating the immune response against infection." (PMID 38543687, 2024). "During the initial stage of infection, an increased number of CD4+CD25+ cells was observed in Ms_Rv1509 infected mice as compared to Ms_Vc or M. bovis_BCG." (PMID 38803374, 2024). "(2007) also indicated that EVs produced by SRDC (a CD8α+CD4− dendritic cell line) treated with T. gondii antigens induced protection against infection in vivo." (PMID 39113589, 2024). "KLRG1+ CD4 T cells peaked 8 days post-infection in spleen, 24 days post-infection in the SG, and 32 days post-infection in blood." (PMID 39150988, 2024). "Activated CD4+ T lymphocytes can activate macrophages, producing cytokines recruited to the site of infection." (PMID 38038457, 2024). "Regarding T cell subsets, current findings indicate a significant decrease in both CD3+ T cells and CD8+ cytotoxic T cells, as well as marginal decrease in CD4+ helper T cells among HAdV-7 infected patients compared to those with HAdV-3 infections." (PMID 39850965, 2024). "Infection of CD4+ T follicular helper cells (TFH), the major HIV reservoir in chronic asymptomatic infection, impairs B cell function in the germinal center, including maturation into plasma cells and long-lived memory B cells." (PMID 38194272, 2024). "The CD4+ T cell count was statistically significant dependent on the route of infection in 2010 and 2016 (Kruskal–Wallis tests: H = 8.46, df = 2, and p = 0.015 and H = 17.66, df = 2, and p < 0.001)." (PMID 39339921, 2024). "The protein level of RACK1 was strikingly elevated in splenic CD4+ T cells within 5 days of infection, implying a biological relevance of this molecule with CD4+ T cell activities and functions." (PMID 39024388, 2024). "A robust influx of cytokine-producing CD4+ T cells was seen in the lungs of vaccinated mice following infection." (PMID 38980038, 2024). "CD4+ T cells (helper T cells) are important in achieving the effective immune response to pathogens and clearance of infections through an integral role in the development and activation of CD8+ T cells and B cells." (PMID 38343550, 2024). "For cell-to-cell infection experiments, similarly infected MDMs were cocultured with the CD4-positive cell line MT4 transduced with renilla luciferase reporter protein." (PMID 38667313, 2024). "Adoptive transfer of sorted CD62Lhi and CD62Llow CD4+ T-cell subpopulations to naïve mice showed that both populations of T cells conferred protection upon a subsequent infection." (PMID 38469319, 2024).
infection (continued). "T cells are direct infection targets of SARS-CoV-2 and especially central/effector memory and cytotoxic CD4+ T cells prevail after infection with a half-life of up to ~ 200 days." (PMID 37924472, 2024). "The cytokines produced by pDCs can induce distinct patterns of CD4+ T-cell polarization depending on both the type of virus and the site of infection." (PMID 38777879, 2024). "CD4+ T lymphocytes limit parasite growth in the early infection stage, while CD8+ T cells are crucial in the later stage." (PMID 39597646, 2024). "In 2020, the differences in the number of the CD4+ T cell count dependent on the route of infection were statistically insignificant (Kruskal–Wallis test: H = 5.94, df = 2, and p = 0.051)." (PMID 39339921, 2024). "By 3 months post-infection, there were also significantly more CD4+ T cells in the gastric tissue in the InsGAStg/tgIl17ra-/- mice compared to infected InsGAStg/tg mice." (PMID 39588838, 2024). "Toward this end, we performed infections in indicator cell lines that express CD4 and one of various co-receptors." (PMID 39006742, 2024). "A. marginale-specific CD4+ T cell responses are functionally impaired throughout infection as indicated by diminished antigen-specific T cell proliferation and IFNγ producing cells and the absence of long-term memory." (PMID 38596123, 2024). "For MZBs, this is already observed at 6 days post infection of T. brucei, when the first parasite peak occurs, and when numbers of follicular B cells (FoBs), CD4+ T cells, and CD8+ T cells temporarily increase, before they also collapse." (PMID 38535532, 2024). "In the UK, people diagnosed with HIV after 50 are often diagnosed late, defined as having a CD4+ count below 350 cells/μl, because of delayed testing and more rapid CD4+ count decline after infection." (PMID 38016172, 2024). "Following B.1.351 infection, we isolated immune cells from the nasal compartment, lungs, and analyzed CD4+ and CD8+ T cells by flow cytometry." (PMID 39178263, 2024). "CD4+ T cell responses in the lungs after infection were also analysed using Spearman’s correlation analysis with lung bacterial burden 4 weeks after challenge." (PMID 38400112, 2024). "First, we reconstructed and tested ancient forms of CD4 at two important nodes in ape speciation, both prior to the infection of chimpanzees and gorillas with these viruses." (PMID 38014262, 2024). "Given the uncertainty regarding the speed of antigen recognition and presentation during early infection, we simulated different scenarios where the CD4+ and CD8+ T cell response was assumed to begin proliferating between 1 and 5 days post-infection." (PMID 39575237, 2024). "An increase in CD4+ lymphocyte CD28 expression was seen in all groups (p < 0.05 for all) apart from pre-operative samples from patients with post-operative infections." (PMID 38655251, 2024). "Identifying T-cell epitopes is crucial because cytotoxic CD8+ T-cells are essential for clearing SARS-CoV-2 and other intracellular viral pathogens, while CD4+ T-cells are relevant for the coordination with other immune cells against infection and disease." (PMID 39772187, 2024). "Interaction with foreign antigens and adjuvants upon infection or vaccination in individuals with ancestral HLA-II alleles, such as HLA-DR15, results in deficient HLA-II-mediated CD4 T-cell presentation and activation." (PMID 39044822, 2024). "During infection, the depletion of CD4 + lymphocytes involves the Th17 CD4 + lymphocyte population, the role of which is to defend against various pathogens at mucosal barriers such as the gastrointestinal tract." (PMID 37982976, 2024). "Research surrounding the immune response to TB has focused on the CD4 T cell response and its role in controlling the infection in macrophages." (PMID 38994354, 2024).
infection (continued). "In particular, control subjects with remote infection and pregnant women with primary infection at the late time point developed higher levels of pp65-specific CD4+ T-cell response than pregnant women with primary infection at the early time point (p < 0.001)." (PMID 39336935, 2024). "By using IF/FISH (fluorescence in situ hybridization) methods, we showed co-localization of HA-tagged ZCCHC3, LSM14A, and the HIV-1 lentivirus gRNA in HeLa CD4+ cells 30 min after infection." (PMID 38384847, 2024). "One MVA-ST/N-vaccinated animal showed a high activated T cell count in the blood after challenge infection, mounting 2.4 × 104 counts/mL for CD4 T cells and 4.3 × 104 counts/mL for CD8 T cells." (PMID 38543782, 2024). "Viral loads, CD4+ T cell counts, infection duration, ART, substance-use-disorder-related toxicities, and opportunistic infections play important roles in disease acceleration." (PMID 38399364, 2024). "During this infection, either the depletion of CD4+ T cells or decreased MHC class II expression reduced protection." (PMID 38793562, 2024). "Due to their location at the site of infection, CD4 TRM can be activated and drive protective inflammatory responses in the lung prior to activation of memory T cells in secondary lymphoid organs." (PMID 38607077, 2024). "The number of CD4+ cells was low in the first two weeks and then remained high from the third week post-infection." (PMID 38474071, 2024). "In terms of disease manifestations, the (productive) infection of CD4+ T-helper cells is the most crucial event, as it results in T-cell depletion, which manifests in a continuous decline in the immune system’s functionality and culminates in its collapse." (PMID 39339243, 2024). "At day 10 post-infection, similar numbers of CD4+ or CD8+ T cells, as well as activated (CD44hi CD62Llo) T cells were found in the lung digests of mice that received either treatment." (PMID 39205245, 2024). "It is also possible to target CCR5 using these nuclease-based tools to render CD4+ cells resistant to infection, as well as silencing CCR5 using short interfering or short hairpin RNA (siRNA or shRNA)." (PMID 38474018, 2024). "In particular, pp65 was the immunodominant target of CD4+ T cells in control subjects with remote infection, whereas gB was the immunodominant target of CD8+ T cells in pregnant women with primary infection at the early time point." (PMID 39336935, 2024). "One of the limitations of this study is that our cohorts were not designed to directly correlate the impact of the observed cytokine CD4+T cell profile with protection against infection." (PMID 39104410, 2024). "While CD4-independent infection has been demonstrated in vitro, such as via an endocytotic route, the infection is far less efficient than in CD4+ T cells." (PMID 39205255, 2024). "Analysis of CD4 cell counts revealed significant differences between subgroups by gender, age, and route of infection." (PMID 39599831, 2024). "Cross-presentation and cross-priming are generally thought to be carried out preferentially by cDC1, whereas cDC2 are known as APCs serving CD4 T lymphocytes both in the setting of infection and cancer." (PMID 39470607, 2024). "These authors also detected a downregulation of CD8 expression on both CD4-CD8+ and CD4+CD8+ thymocytes at one week after infection." (PMID 39066253, 2024). "Only two studies have described prolonged infection in individuals with normalized CD4 counts and undetectable viral loads, though the mechanism of SARS-CoV-2 persistence in these patients was not explored." (PMID 37821620, 2024). "L'infection VIH1 était découverte à un taux moyen de CD4 de 284,5/mm3 (extrêmes : 6 et 584, IC), passant à 566,6/mm3 (extrêmes 350 et 900, IC) après traitement antirétroviral hautement actif (HAART) détaillé dans le Tableau III." (PMID 40070975, 2024).
infection (continued). "In both monocytes and CD4+ T cells, CL8-infected cells upregulated ISGs to a greater extent than 170-infected cells, suggesting deficient expression of ISGs upon infection with SIVMne170." (PMID 38317183, 2024). "It has been suggested that these two diseases exhibit a similar immune response in the face of infection, exhibiting inflammation the infiltration of CD4+ T-cells under cytophagy by the antigen IGAs." (PMID 38335208, 2024). "Partial depletion of CD4 T cells around the time of infection results in a stable Th1 response, control of parasitemia and so in resistance." (PMID 38611110, 2024). "There was also weak CD4+ T-cell staining at 15 days post-infection and greatly increased IgD+ B-cell staining compared to 30 days post-infection, indicating a massive expansion of naïve B cells." (PMID 38514468, 2024). "Protective host immune responses induced by natural infection or vaccination consist of humoral responses, such as neutralizing antibodies (nAbs), as well as cellular responses including CD4+/CD8+ T cell responses specific to SARS-CoV-2 antigens." (PMID 38198521, 2024). "Through our investigations, we uncovered that during the initial stages of infection, endogenous Treg cells play a role in suppressing the expansion of CD4+ T cells and the development of anti-parasite effector CD8+ T cell responses." (PMID 38683845, 2024). "Among the 9 patients with CD4+T lymphocyte counts ranging from 50 to 200 cells/μL, 3 patients exhibited co-infections in the test results, 4 patients displayed single-pathogen infections, and 2 patients showed pathogen negativity." (PMID 38774626, 2024). "The finding proves that CD4 cells play a central role in activating both humoral and cellular immune responses of patients' bodies tofight against infection." (PMID 38410498, 2024). "The study revealed that the frequencies of elevated NfL levels among PWH with HAD, neuroasymptomatic PWH with a CD4+ T-cell count below 50, and those within the first year of infection were 100%, 75% and 40%, respectively." (PMID 39066244, 2024). "We thus tested primary CD4+ T cells isolated from human umbilical cord blood for the induction of apoptosis, following infection with the WT and mutant viruses." (PMID 39459974, 2024). "During cell-mediated immunity, CD4+ T cells are recruited to the infection site and are activated by MHC class II antigen presentation on APCs." (PMID 39698320, 2024). "We further demonstrated that activation induced upregulation of CD4 expression on Vδ2 T cells directly increasing permissibility to infection." (PMID 39149467, 2024). "Ccr7+Ido1+ DCs, Cd160+Cd8+ T cells, and Tnfrsf4+Cd4+ T cells all increased after infection, and were viral RNA-positive, suggesting direct involvement of these immunity hubs against SARS-CoV-2 infection." (PMID 39414763, 2024). "Clinically, acute HIV infection manifests in heterogeneous flu-like symptoms that occur days to a few weeks after infection and are accompanied by high viremia levels and a significant decline in CD4+ T cell numbers." (PMID 38400997, 2024). "As in the primary CD4+ T cells, we observed a dose-dependent increase in infection, though higher concentrations again resulted in viability defects." (PMID 39259751, 2024). "While macrophages and dendritic cells are the primary producers of TNF-α during infection, CD4+ T cells also contribute significantly to its production." (PMID 39770852, 2024). "The increasing SN-/Dim cell population observed through the defined stages during infection indicates that Sial α2,6 downregulation is related to CD4+ and CD8+ activation progress." (PMID 39253089, 2024). "To address this, we nucleofected Cas9/single-guide RNA (sgRNA) ribonucleoprotein (RNP) complexes targeting GATA3 or FOXP1 into HIV-GFP-infected primary CD4+ T cells at 1 week post infection." (PMID 38902848, 2024).
infection (continued). "We demonstrated that mito‐transfer can enhance control of viral and non‐viral pathogen infections in vivo, and the enhanced protection is likely related to the preferential generation of antigen‐specific effector memory CD4+ T cells." (PMID 37990641, 2024). "At T1, BA.5 breakthrough infection effectively expanded both CD4+ T cell (3.73-fold, P < 0.0001) and CD8+ T cell (5.45-fold, P < 0.0001) responses specific to the BA.5 spike." (PMID 38456703, 2024). "Two days post-infection, cells were stained for surface CD4 before fixation and permeabilization to enable detection of the HIV-1 p24 antigen and HIV-1 mRNAs." (PMID 39373535, 2024). "At 3 weeks post infection, CD4 T cells from infected C57BL/6 mouse were transferred via the intravenous route to the RAG1 KO mice." (PMID 38977711, 2024). "Taken together, SARS-CoV-2-infected individuals can develop substantial SARS-N-specific CD8+ and CD4+ T-cells early after infection, but the longevity of SARS-N-specific memory T-cells needs to be studied further." (PMID 38543812, 2024). "By similar mechanisms, migratory conventional DCs (cDCs) contribute to transferring the virus to CD4 + T cells and to secondary lymphoid organs, while follicular DCs (fDCs) maintain germinal centers and trap HIV, enhancing susceptibility to infection." (PMID 39609320, 2024). "In mouse-infection with C. trachomatis, CD4 T cells are both necessary and sufficient to clear infection and to protect against re-infection." (PMID 39206090, 2024). "Infection of the thymus with human and mouse roseoloviruses, belonging to the herpesvirus family, results in a temporary reduction of CD4+ SP and CD4+CD8+ DP thymocytes." (PMID 38571951, 2024). "HIV-1 envelope (Env) components activate the mTOR pathway in dendritic cells, which serves to suppress dendritic cell autophagy and allow infection transfer to CD4+ T cells." (PMID 39086659, 2024). "Consistent with the requirement for RACK1 in conventional T cell proliferation in vitro, we observed that deletion of RACK1 led to a remarkably reduced proportion and absolute number of splenic CD4+ T cells at day 7 post-infection (p.i.)." (PMID 39024388, 2024). "As part of pathogen-specific immune responses, naïve CD4+ T cells differentiate into effector subsets which perform specialized activities to orchestrate immune-mediated clearance of infection." (PMID 39267766, 2024). "As well as highlighting the nature of these protective late-rising T cells induced by natural infection, our data represent the first report of a CD4 T cell-centric CMV vaccine strategy." (PMID 38236791, 2024). "Based on the results of univariate logistic regression analysis, we selected three independent variables with p-values < 0.1 for subsequent multivariate logistic regression analysis: CD4 cell count, subtype, and year of infection." (PMID 39420358, 2024). "Further, analysis of cytokine production revealed similarly upregulated CD4+IL-17A+, CD4+IFNγ+, and CD4+IL-22+ T cells in the colons of RORγtK256R/K256R and WT mice after infection." (PMID 39504243, 2024). "The second stage is transitional, comprising approximately 15–25 days post infection (dpi), and is marked by an accumulation of monocytes and their differentiation in the lung parenchyma, together with the appearance of effector CD4 and CD8 T cells." (PMID 38701094, 2024). "T cell responses after a breakthrough infection were similar in healthy controls and patients on TNFi after three vaccine doses (healthy control CD4, 0.110% (0.063–0.204); CD8, 0.024% (0.009–0.057))." (PMID 39260039, 2024). "This was confirmed by inoculating the CD4 T cell line TZMBL1 (which express lacZ under control of the HIV-1 promoter) with supernatants collected from infected cells after 96 hours post infection (hpi)." (PMID 38924030, 2024). "The mice were adoptively transferred with I-Ab-restricted LCMV glycoprotein (gp)-specific SMARTA CD4 T cells, followed by infection with LCMV Armstrong (LCMVArm)." (PMID 39720725, 2024).